NDRG3 (NDRG family member 3)
Tractability: PROTAC: ubiquitination databases record sites on it; its protein half-life has been measured.
Gene: Protein-coding gene on chromosome 20 (36,651,766 to 36,746,128, reverse strand). Ensembl gene ENSG00000101079.
Subcellular location (Human Protein Atlas): Cytosol; Vesicles
Gene Ontology:
Biological process: cell differentiation; negative regulation of cell growth; signal transduction; spermatogenesis; decidualization
Cellular component: cytoplasm; extracellular exosome
Genetic constraint (gnomAD): Loss-of-function variants: 15 observed, 35.06 expected, observed/expected ratio (o/e) 0.43, 90% interval 0.28 to 0.66. The synonymous counts are far from expectation, so gnomAD's model fits this gene poorly and the ratio says little. Missense variants: 273 observed, 350.66 expected, observed/expected ratio (o/e) 0.78, 90% interval 0.7 to 0.86. Synonymous variants: 99 observed, 131.24 expected, observed/expected ratio (o/e) 0.75, 90% interval 0.64 to 0.89.
Homologues: Orthologues: chimpanzee NDRG3 (100% identical), macaque NDRG3 (99% identical), dog NDRG3 (97% identical), rat LOC120101770 (97% identical), guinea pig NDRG3 (96% identical), mouse Ndrg3 (96% identical), rabbit NDRG3 (94% identical), pig NDRG3 (89% identical), zebrafish ndrg3b (78% identical), tropical clawed frog ndrg3 (75% identical), zebrafish ndrg3a (75% identical), Drosophila melanogaster MESK2 (40% identical), and 3 more. Paralogues in human: NDRG1 (66% identical), NDRG4 (59% identical), NDRG2 (57% identical).
Diseases named in the same sentence as NDRG3 in open-access papers:
NDRG3 is named in the same sentence as 35 diseases in open-access papers, as found by Europe PMC text mining. Sharing a sentence is not in itself a finding about the gene and the disease. The quoted sentences say what the papers report.
hepatocellular carcinoma (7 papers, 2018 to 2025). A malignant tumor that arises from hepatocytes. "Animal experiments showed that knockdown of NDRG3 inhibited the proliferation of hepatocellular carcinoma (HCC) subcutaneous tumors and angiogenesis of subcutaneous stromal plugs." (PMID 39934144, 2025). "In hepatocellular carcinoma cells, the NDRG3 protein expression is highly correlated with the activity of angiogenesis, anti-apoptosis, and proliferation via analyzing the genomic activity." (PMID 36612084, 2022). "With the knockdown of the NDRG3 gene in hepatocellular carcinoma, the phosphorylation of C-Raf and B-Raf (at Ser445) is abrogated, and in consequence, the blocked angiogenesis and hypoxic cell growth." (PMID 36612084, 2022). "The results of Wang showed that the expression of NDRG3 is up-regulated in hepatocellular carcinoma cells, which reversing the malignant phenotype of hepatocellular carcinoma cells." (PMID 36619553, 2022). "NDRG3 is overexpressed in hepatitis B virus (HBV)-related hepatocellular carcinoma, and as such, it is a potential therapeutic target for HCC." (PMID 30413609, 2018). "On the other hand, NDRG3 expression is frequently upregulated in many cancer types, including prostate cancer, hepatocellular carcinoma, nonsmall cell lung cancer, breast cancer, and colorectal cancer, in association with aggressive cancer phenotypes and a poor prognosis." (PMID 35563842, 2022). "Previous studies have demonstrated thatmiR-122inhibits hepatitis B virus (HBV) replication by targeting NDRG3 in hepatocellular carcinoma cells (HCC) or HCC-derived cell lines." (PMID 35632672, 2022). "The present study analyzed NDRG3 expression in hepatocellular carcinoma (HCC) and explored the relationship between expression of NDRG3 in HCC patients and their clinicopathological characteristics." (PMID 30413609, 2018). "Moreover, recent studies have indicated that human miR-122 significantly facilitated hepatitis C virus (HCV) replication, whereas miR-122 by targeting NDRG3 inhibits hepatitis B virus (HBV) replication in human hepatocellular carcinoma (HCC) and HCC-derived cell lines." (PMID 35632672, 2022). "In addition, exogenous L-lactate treatment can also induce the N-myc downstream-regulated gene family member 3 (NDRG3)/Raf/ERK hypoxia signaling axis to stimulate the angiogenesis and tumor growth of hepatocellular carcinoma cells." (PMID 36612084, 2022).
prostate carcinoma (5 papers, 2018 to 2022). A carcinoma that arises from epithelial cells of the prostate gland. "Then a pro-tumorigenic activity was reported for a member of the NDRG family, NDRG3, when it was known to be associated with prostate cancer." (PMID 31935861, 2020). "NDRG3 promoted prostate cancer cell growth, along with the upregulation of angiogenic chemokine expression and facilitated colorectal cancer metastasis by activating Src phosphorylation." (PMID 35563842, 2022). "In particular, NDRG3 is closely related to proliferation and migration of prostate cancer cells, and recent studies reported its implication in lactate-triggered hypoxia responses or tumorigenesis." (PMID 31935861, 2020). "NDRG3 is upregulated in epithelial prostate cancer cells and prostatic stromal cells at both mRNA and protein levels, and overexpression of NDRG3 induces cell proliferation and migration." (PMID 31935861, 2020). "The overexpression of CXCL3 and its receptor CXCR2 promoted the proliferation and migration of cancer cells by regulating the expression of genes, including ERK, BAX, TP73, and NDRG3, which enhance the oncogenic potential of prostate cancer." (PMID 30686982, 2018). "However, studies have found that NDRG3 is highly expressed in gastric and prostate cancer, while low expression in breast cancer and oral squamous cell carcinoma." (PMID 36619553, 2022). "NDRG3 overexpression is also thought to be correlated with non-small cell lung cancer (NSCLC), prostate cancer, and laryngeal squamous cell carcinoma." (PMID 30413609, 2018).
breast carcinoma (4 papers, 2017 to 2024). "Much less is known about the role of NDRG3 in breast cancer, with only two studies published to date; one of those studies has reported a potential tumor suppressor function and the other a tumor promoter role for NDRG3." (PMID 38611020, 2024). "In another breast cancer study, the expression of NDRG3 protein is increased, which is related to the invasive biological phenotype and poor prognosis of patients with invasive breast cancer." (PMID 36619553, 2022). "For example, the description of NDRG3 is inconsistent in the study of breast cancer and liver cancer." (PMID 36619553, 2022). "The expression of NDRG3 is down-regulated in breast cancer patients, especially in the late stage of the disease." (PMID 36619553, 2022). "In contrast, some studies have indicated that NDRG3 expression was decreased in some tumor types, such as breast cancer, and thus appeared to function as tumor suppressors." (PMID 30413609, 2018). "Based on the results of previous studies, we chose the miR-122 target genes ADAM10, Bcl-w, VEGFC, PKM2, NOD2, IGF1R and NDRG3 to explore the downstream genes in breast cancer." (PMID 29200969, 2017). "In the first of these studies, Estiar and colleagues analyzed tissue samples from 88 patients and found that NDRG3 was downregulated in patients with breast cancer, and that patients with a low tumor expression of NDRG3 had worse outcomes than those with a high NDRG3-expressing tumors." (PMID 38611020, 2024). "Specifically, we observed NDRG1 amplification in 23% of breast cancer samples, whereas NDRG2 was amplified in 0.9% cases, NDRG3 in 2.5% and NDRG4 in 0.3%." (PMID 38611020, 2024). "NDRG2 has been described mostly as a tumor suppressor, and more information is needed regarding the functions of NDRG3 and NDRG4 in breast cancer." (PMID 38611020, 2024).
gastric cancer (4 papers, 2017 to 2025). A primary or metastatic malignant neoplasm involving the stomach. "Compared with other NDRG members, NDRG3 is less studied, with limited evidence showing that it can act as a tumor promoter in patients with gastric cancer and is associated with histologic grade and poor patient survival." (PMID 40378957, 2025). "A study has detected that NDRG3 was upregulated in patient tissues with gastric cancer and contributed to 5-fluorouracil drug resistance in gastric cancer cell lines." (PMID 40378957, 2025). "For example, low expression of miR-29a-5p in gastric cancer can regulate NDRG3, further increasing cancer cell resistance to the chemotherapeutic drug 5-fluorouracil." (PMID 39519347, 2024). "Our qRT-PCR results showed the expression of AM, VEGFA, NDRG3, and HIF-1α allincreased, though to different degrees, and at different times, in the gastric cancer cell lines." (PMID 29179449, 2017). "Under hypoxic conditions, the expression of AM, HIF-1α, NDRG3, and VEGFA are significantly elevated in the human gastric cancer cell line BGC-823." (PMID 29179449, 2017).
Cerebral ischemia (3 papers, 2019 to 2021). Restriction of arterial blood supply to the brain associated with insufficient oxygenation to support the metabolic requirements of the tissue. "In the experiment of cerebral ischemia and hypoxia in rats, let-7f was found to be the upstream regulatory factor of NDRG3." (PMID 34679939, 2021). "After an initial increase of NDRG4, decreased levels of NDRG4 were observed, resembling the expression of NDRG2 and NDRG3 during cerebral ischemia." (PMID 31485792, 2019). "NDRG3 appears to be a hypoxia-responsive gene that is upregulated during cerebral ischemia in rats." (PMID 31485792, 2019). "NDRG2, NDRG3, and NDRG4 also seem to be involved in brain ischemia." (PMID 31485792, 2019).
colorectal cancer (3 papers, 2018 to 2022). A primary or metastatic malignant neoplasm that affects the colon or rectum. "Limited studies on NDRG3 and NDRG4 revealed that NDRG4 plays tumor suppressive roles in colorectal cancer and glioblastoma." (PMID 30413609, 2018).
invasive breast carcinoma (3 papers, 2022 to 2025). A carcinoma that infiltrates the breast parenchyma. "Overexpression of NDRG3 is associated with poorer overall survival in patients with invasive breast cancer, with it promoting metastasis by inducing Src phosphorylation in colorectal cancer." (PMID 40378957, 2025). "The expression of NDRG3 has also been demonstrated to be related to poor patient outcomes in invasive breast cancer." (PMID 40378957, 2025).
bladder carcinoma (2 papers, 2015 to 2019). "Our study is the first study to demonstrate the modulations of NDRG1, NDRG2, and NDRG3 gene expressions by GDF15 in bladder carcinoma cells." (PMID 26249737, 2015). "Upregulations of MASPIN, NDRG1, NDRG2, and NDRG3 expressions may account for the antitumor characteristics of GDF15 in human bladder carcinoma cells." (PMID 26249737, 2015). "The expressions of mammary serine protease inhibitor (MASPIN) and N-myc downstream-regulated family genes (NDRG1, NDRG2, and NDRG3) were upregulated by GDF15 overexpressions and rhGDF15 treatments in bladder carcinoma cells." (PMID 26249737, 2015). "Nowadays, no report has yet described the expression or regulation of NDRG3 in bladder cancer." (PMID 26249737, 2015).
liver cancer (2 papers, 2016 to 2022). An epithelial or non-epithelial malignant neoplasm that arises from the liver. "The expression of NDRG3 change the sensitivity of cancer cells to chemotherapeutic drugs, which may be a potential therapeutic strategy for the treatment of liver cancer in the future." (PMID 36619553, 2022). "Regarding NDRG3, although some studies reported that NDRG3 might be an oncogene in prostate and liver cancers, the expressions and functions of NDRG3 gene in OSCC cells have yet to be investigated." (PMID 27589737, 2016). "Although previous studies indicated that NDRG3 overexpression might increase cell growth, angiogenesis, tumorigenesis, and metastasis in prostate and liver cancers, the function of NDRG3 is still not well understood in OSCC." (PMID 27589737, 2016).
viral infection (2 papers, 2023 to 2026). "CD8+ T cells lacking NDRG3 exhibit severely impaired expansion in vivo in response to both viral infections and tumor challenges." (PMID 42136568, 2026).
Alzheimer disease (1 paper, 2025). A progressive, neurodegenerative disease characterized by loss of function and death of nerve cells in several areas of the brain leading to loss of cognitive function such as memory and language. "On the contrary, the expression of the other two NDRG family members, NDRG3 and NDRG4, were lower in the brains of patients with Alzheimer’s disease relative to human normal adult brain." (PMID 40378957, 2025).
astrocytoma (1 paper, 2021).
breast tumor (1 paper, 2024). "Thus far, no pathway has been identified as supporting a role for NDRG3 being either a breast tumor suppressor or promoter." (PMID 38611020, 2024).
chronic myelogenous leukemia (1 paper, 2025). "In chronic myelogenous leukemia, NDRG3 has been demonstrated to associate with imatinib resistance via promoting nuclear accumulation of β-catenin." (PMID 40378957, 2025). "A recent study demonstrated that NDRG3 regulates imatinib resistance by promoting nuclear β-catenin accumulation in chronic myelogenous leukemia (CML)." (PMID 40378957, 2025).
colitis (1 paper, 2017). Inflammation of the colon. "Since we could not detect upregulation of Hif1α signaling in the course of the colitis starvation-refed group, regulation of NDRG3 gene expression in the colon needs further investigation." (PMID 28955126, 2017).
glycogen storage disease (1 paper, 2022). "Mice with liver-specific KO of NDRG3 (Ndrg3 LKO) exhibited glycogen storage disease (GSD) phenotypes including excessive hepatic glycogen accumulation, hypoglycemia, elevated liver triglyceride content, and several signs of liver injury." (PMID 35563842, 2022).
Hip dysplasia (1 paper, 2024). The presence of developmental dysplasia of the hip. "We identified a significantly associated locus for hip dysplasia on chromosome 24, with three equally associated SNPs (p = 4.3 × 10-7) in complete linkage disequilibrium located within NDRG3, a gene which in humans has been shown to be differentially expressed in osteoarthritic joint cartilage." (PMID 38480780, 2024).
Hypoglycemia (1 paper, 2022). A decreased concentration of glucose in the blood. "Collectively, these results indicate that the malfunctioning of PYGL due to the downregulation of gene expression and suppression of enzymatic activity in hepatocytes could be the primary cause of aberrant hepatic glycogen accumulation and hypoglycemia in Ndrg3 LKO mice." (PMID 35563842, 2022). "In our results describing age-dependent glucose–glycogen flux, it is notable that at 2 months of age, Ndrg3 LKO mice exhibited hypoglycemia and lower intrahepatic glucose levels without showing significant changes in fasting hepatic glycogen content compared to WT." (PMID 35563842, 2022).
Infertility (1 paper, 2017). "Haplo-insufficiency of Ndrg3 gene led to sub-infertility during the male early maturation." (PMID 28290521, 2017).
lymph node metastasis (1 paper, 2022). "The level of serum NDRG3 in patients with lymph node metastasis and extrathyroidal extension PTC was significantly lower than that in patients without lymph node metastasis (P =0.019) and extrathyroidal extension (P =0.007)." (PMID 36619553, 2022). "The median value of serum NDRG3 in PTC patients with extrathyroid extension and lymph node metastasis was significantly lower than that in PTC patients without both." (PMID 36619553, 2022).
ovarian carcinoma (1 paper, 2020). A malignant neoplasm originating from the surface ovarian epithelium. "To further investigate the specific effects of NDRG2 on ovarian cancer cells, we conducted NDRG2 overexpression and NDRG2 silence in SKOV3, OVCAR-3, and CAOV3 cells by transfection with vector (negative control), NDRG2 OE, si-NC (negative control), or si-NDRG3." (PMID 32345304, 2020).
thyroid cancer (1 paper, 2022). "In addition, the study found that some BTN may have genetic changes, leading to metabolic changes, similar to thyroid cancer, so the NDRG3 detectable in BTN is reduced, but there is no more evidence to support this view." (PMID 36619553, 2022).
thyroid papillary carcinoma (1 paper, 2022). "Enzyme-linked immunosorbent assay was used to detect the serum NDRG3 expression in 81 papillary thyroid carcinoma cases, 75 benign thyroid nodules cases and 77 healthy control cases, respectively." (PMID 36619553, 2022). "Only the expression of serum NDRG3 was significantly different between benign thyroid nodules and papillary thyroid carcinoma groups (P <0.001)." (PMID 36619553, 2022). "Immunohistochemical staining was used to detect the expression of NDRG3 in papillary thyroid carcinoma, benign thyroid nodules and normal tissues adjacent to cancer." (PMID 36619553, 2022). "Logistic regression analysis showed that serum NDRG3 was an independent protective factor for papillary thyroid carcinoma (OR =0.964, 95%CI =0.953 to 0.974, P <0.001)." (PMID 36619553, 2022). "Immunohistochemistry showed that NDRG3 was expressed in all three groups, the lowest in papillary thyroid carcinoma, the second in benign thyroid nodules, and the highest in normal tissues adjacent to cancer." (PMID 36619553, 2022). "The ROC curve of non-papillary thyroid carcinoma diagnosed by serum NDRG3 showed the optimal cut-off value of 481.38 pg/ml, sensitivity of 72.4%, specificity of 90.1%, and the maximum area under the curve (AUC =0.902, 95%CI =0.863 to 0.940, P <0.001)." (PMID 36619553, 2022). "The expression level of serum NDRG3 was significantly correlated with extrathyroid extensionand (P =0.007) and lymphatic metastasis of papillary thyroid carcinoma (P =0.019)." (PMID 36619553, 2022). "The expression of serum triiodothyronine, tetraiodothyronine, thyrotropin, thyroglobulin antibody and thyroid peroxidase antibody and NDRG3 were significantly different among benign thyroid nodules, papillary thyroid carcinoma cases and healthy control groups (P <0.001)." (PMID 36619553, 2022). "The decrease of NDRG3 expression can not only differential diagnosis benign thyroid nodules and papillary thyroid carcinoma, but also serve as a molecular marker for the diagnosis of papillary thyroid carcinoma." (PMID 36619553, 2022).